MTSS1 (MTSS I-BAR domain containing 1)
Diseases named in the same sentence as MTSS1 in open-access papers (continued):
Sharing a sentence is not in itself a finding about the gene and the disease.
glioma (9 papers, 2020 to 2025). A benign or malignant brain and spinal cord tumor that arises from glial cells (astrocytes, oligodendrocytes, ependymal cells). "However, the molecular mechanisms of MTSS1 associated with invasion and metastasis of glioma was poorly understood." (PMID 32913477, 2020). "In this study, we hypothesized the downregulation of MTSS1 expression in gliomas may be associated with miRNAs." (PMID 32913477, 2020). "Further functional analysis has revealed that MTSS1 is downregulated in both glioma cells and tissues." (PMID 39553554, 2024). "The combined findings have provided reasonable insights into the pivotal roles played by the MEG3/miR-96-5p/MTSS1 axis in controlling the progression of glioma." (PMID 39553554, 2024). "In consistence with these findings, MTSS1 was also identified as a putative tumor suppressor in glioma cells." (PMID 38021156, 2023). "MiRNAs can negatively influence MTSS1 expression, thereby facilitating the invasion and metastasis of glioma cells." (PMID 36457281, 2023). "The results indicated that miR-182-5p was the novel target of circRNA_103239 in glioma, and MTSS1 was the putative downstream molecule of circRNA_103239/miR-182-5p axis." (PMID 38021156, 2023). "To evaluate the role of MTSS1 in glioma occurrence and progression, we selected the grade IV glioma cell lines U87MG and T98G as the research model." (PMID 32913477, 2020). "The higher the degree of malignancy of a glioma, the lower was the level of MTSS1 protein in the brain tissue." (PMID 32913477, 2020). "The results of this study preliminarily suggested the expression pattern and possible biological function of the miR-182/MTSS1 signaling axis in glioma." (PMID 32913477, 2020). "Then we assessed the expression of miR-182 in glioma tissues and analyzed its relationship with MTSS1 expression." (PMID 32913477, 2020). "The expression of MTSS1 was closely related to the grade of the gliomas—the higher the degree of malignancy, the lower was the expression of MTSS1." (PMID 32913477, 2020). "In conclusion, we believed that miR-182 modulates glioma cell migration and invasion by targeting the MTSS1 and suggested that miR-182 was a potential therapeutic target for gliomas." (PMID 32913477, 2020). "Further experiments showed that after functional inhibition of miR-182 in glioma cells, the expression of MTSS1 was significantly upregulated." (PMID 32913477, 2020). "It was also literature reported that MTSS1 was regulated by epigenetics in glioma cells and inhibits glioma cell motility." (PMID 32913477, 2020). "Considering the possible role of MTSS1 in tumorigenesis and development, this study preliminarily investigated the expression and biological function of MTSS1 and the mechanism regulating its expression in human gliomas." (PMID 32913477, 2020). "Considering the downregulation of MTSS1 expression in glioma tissue and its biological function of inhibiting the proliferation and invasion of glioma cells, it is necessary to explore the molecular mechanism underlying MTSS1 downregulation." (PMID 32913477, 2020). "The expression of MTSS1 in glioma tissues was significantly lower than that in the matched paracancerous tissues." (PMID 32913477, 2020). "In addition, glioma cells were transfected with miR-182-5p inhibitors, where the levels of MTSS1 were remarkably elevated." (PMID 38021156, 2023). "The putative circRNA_103239/miR-152-5p/MTSS1 axis could be the novel candidate for the targeted therapies in the treatment of glioma." (PMID 38021156, 2023). "Furthermore, miR-182-5p was the novel target of circRNA_103239 in glioma, and MTSS1 was the putative downstream molecule of circRNA_103239/miR-182-5p axis." (PMID 38021156, 2023). "Moreover, the expression of MTSS1 was remarkably reduced at both mRNA and protein levels in glioma cells transfected with miR-182-5p mimics." (PMID 38021156, 2023). "Furthermore, the expression of MTSS1 was significantly decreased in glioma samples compared with para-carcinoma controls." (PMID 38021156, 2023).
glioma (continued). "In addition, the levels of MTSS1 were notably elevated in glioma cells transfected with LV-circRNA_103239." (PMID 38021156, 2023). "In addition, the expression of miR-182-5p and MTSS1 was reversely correlated in glioma specimens, where the expression of circRNA_103239 and MTSS1 was positively correlated." (PMID 38021156, 2023). "Furthermore, MTSS I‐BAR domain containing 1 (MTSS1) is important for inhibiting the proliferation and invasion of glioma cells, while TGF‐β1 induces EMT." (PMID 36457281, 2023). "At the same time, it is found that circRNA_104948/miR-29b-3p/MTSS1/DNMT3B pathway may be a potential candidate for targeted therapy in patients with glioma." (PMID 37934565, 2023). "Their discoveries uncovered the significant contributions of circRNA_104948 in the progression of glioma, highlighting that the circRNA_104948/miR-29b-3p/MTSS1/DNMT3B pathway holds promise as a potential therapeutic target for individuals diagnosed with glioma." (PMID 37705098, 2023). "Additionally, circRNA_103239 suppressed the progression of glioma in a miR-182-5p/MTSS1 dependent manner." (PMID 38021156, 2023). "Furthermore, a miR-182 inhibitor induced glioma cell proliferation and invasion by increasing MTSS1 expression." (PMID 32913477, 2020). "MTSS1 is epigenetically regulated and inhibits the movement of glioma cells." (PMID 32913477, 2020). "Biochemical analyses suggested that miR-182 may target MTSS1 and that miR-182 expression is negatively correlated with MTSS1 expression in glioma tissues." (PMID 32913477, 2020). "Considering the significant downregulation of MTSS1 expression in human gliomas and its important role in the proliferation and invasion of glioma cells, it is necessary to explore the molecular mechanism underlying the downregulation of MTSS1 expression in human gliomas." (PMID 32913477, 2020). "In our present study, we aimed to investigate the expression pattern and biological function of Metastasis suppressor protein 1(MTSS1) in glioma and to further explore whether miRNAs were involved in the deregulation of MTSS1." (PMID 32913477, 2020). "Our research revealed that MTSS1 participates in TGF‐β1‐induced EMT in glioma cells and miR-182 may work as an important biological target regulating MTSSI in proliferation and invasion of glioma cells." (PMID 32913477, 2020). "Moreover, functional inhibition of miR-182 suppressed the proliferation and invasion of glioma cells, similar to overexpression of MTSS1." (PMID 32913477, 2020). "Therefore, our study laid a solid foundation for the diagnosis and treatment of glioma through understanding the function and mechanisms of MTSS1 in glioma." (PMID 32913477, 2020). "Therefore, the circRNA_103239/miR-182-5p/MTSS1 axis could be a novel therapeutic target for the treatment of glioma." (PMID 38021156, 2023). "To investigate whether MTSS1 was involved in the development of human gliomas, we first detected the expression of MTSS1 in 34 human glioma and matched normal tissues, specifically, 5 grade I glioma tissues, 8 grade II glioma tissues, 12 grade III glioma tissues and 9 grade IV glioma tissues." (PMID 32913477, 2020). "MTSS1 regulated the EMT process induced by TGF-β1 to inhibit the proliferation and invasion of glioma cells." (PMID 32913477, 2020). "However, whether miR-182 can directly target MTSS1 and affect the progression of glioma is unclear." (PMID 32913477, 2020). "In glioma cells, downregulation of METTL14 induces down-regulation of m6A modification and expression of circRNA_103239, driving up-regulation of miR-182-5p and down-regulation of MTSS1, thereby promoting EMT in glioma and promoting tumor progression." (PMID 41256854, 2025). "The protein level of MTSS1 in glioma tissue was significantly decreased compared with that in normal brain tissue." (PMID 32913477, 2020). "To confirm whether miR-182 directly regulates the expression of MTSS1, we first introduced a miR-182 inhibitor and its NC inhibitor into U87MG and T98G glioma cells." (PMID 32913477, 2020).
acute myeloid leukemia (5 papers, 2015 to 2023). Acute myeloid leukemia (AML) is a group of neoplasms arising from precursor cells committed to the myeloid cell-line differentiation. "In acute myeloid leukemia, MTSS1 is downregulated and the low expression of MTSS1 is associated with poor patient prognosis, chemotherapy resistance, and disease aggressiveness." (PMID 37920825, 2023). "Taken together, these data suggest that MTSS1 potentially can be targeted pharmacologically in the treatment of patients with acute myeloid leukemia and chronic myeloid leukemia, which of course could be of interest also for epithelial cancers with low MTSS1 expression." (PMID 37920825, 2023).
lung adenocarcinoma (5 papers, 2020 to 2024). A carcinoma that arises from the lung and is characterized by the presence of malignant glandular epithelial cells. "In the context of lung adenocarcinoma, MTSS1 interacts with the E3 ligase AIP4 to monoubiquitinate PD-L1 at lysine 263, which targets it for lysosomal degradation." (PMID 39625546, 2024). "Another control of MTSS1 was proposed by the observed interaction between the LINC00491 long non-coding RNA and MTSS1 in lung adenocarcinoma (LUAD)." (PMID 39625546, 2024). "Here, we find that MTSS1 is downregulated in lung adenocarcinoma, leading to PD-L1 upregulation, impairment of CD8+ lymphocyte function, and enhanced tumor progression." (PMID 36810288, 2023). "In addition, EGFR-KRAS signaling in lung adenocarcinoma suppresses MTSS1 and upregulates PD-L1." (PMID 36810288, 2023).
breast tumor (4 papers, 2016 to 2025). "We further found that the expression of MTSS1, a tumor suppressor, was decreased in human breast tumors." (PMID 40066676, 2025). "Since the sample size in our study was relatively small, future studies are necessary to collect and use large population sizes to confirm the corelative expression of SNHG15 and MTSS1 mRNA in human breast tumors." (PMID 39519115, 2024). "We then collected some discarded human breast tumor samples and normal paracancerous tissues and utilized a qRT-PCR approach to examine the co-relative expression of MTSS1 mRNA and SNHG15." (PMID 39519115, 2024). "In addition, we observed that MTSS1 expression was increased by Arid4a over time in breast tumor cells." (PMID 40066676, 2025). "Furthermore, our IHC results confirmed that the expression of MTSS1 is greater in human breast tumor tissues highly expressing Arid4a." (PMID 40066676, 2025). "Previous study demonstrated that p63 could control the cell migration and invasion by regulating the MTSS1 expression in breast tumor cells." (PMID 27230279, 2016). "The half‐lives of metastasis‐suppressing mRNAs, including MTSS1, TIMP2, RB1, and PTEN, were prolonged by approximately 1‐fold in Arid4a‐overexpressing breast tumor cells." (PMID 40066676, 2025). "Notably, the expression of metastasis‐suppressing genes, including MTSS1, TIMP2, Rb1, and PTEN, was increased according to the expression of Arid4a in breast tumor tissues." (PMID 40066676, 2025). "MTSS1, TIMP2, RB1, and PTEN were selected as targets of Arid4a in breast tumor cells for further study for two main reasons: (i) they are among the genes most highly regulated by Arid4a in breast tumor cells; and (ii) they are known typical metastasis inhibitory genes." (PMID 40066676, 2025). "The preliminarily investigation on human tumors further showed that the negative connection between SNHG15 and MTSS1 mRNA might also occur in human breast tumor tissues." (PMID 39519115, 2024). "Notably, in three human breast tumors datasets, the MTSS1/p63 co-expression is a negative prognostic factor on patient survival." (PMID 31159154, 2019).
head and neck squamous cell carcinoma (4 papers, 2014 to 2019). A squamous cell carcinoma that arises from any of the following anatomic sites: lip and oral cavity, nasal cavity, paranasal sinuses, pharynx, larynx, and salivary glands. "In addition, in head and neck squamous cell carcinoma cells, MTSS1 was found to interact with the epidermal growth factor (EGF), strengthen the localization of the EGF receptor in the cell membrane, prolong the Erk signal and promote cell proliferation." (PMID 25295101, 2014).
lung carcinoma (4 papers, 2016 to 2025). "In addition, low MTSS1 expression levels in lung cancer tumors were associated with reduced patient BM survival." (PMID 30224667, 2018). "In contrast, the MTSS1 gene has been shown to exhibit both tumor suppression and tumor-promoting function in lung cancer, depending on the tumor subtype." (PMID 41441397, 2025). "Immunofluorescent staining also confirmed the colocalization of MTSS1 with these markers in lung cancer cells." (PMID 36810288, 2023). "MTSS1 was knocked down in the human H1975 lung cancer cell line, followed by inoculation of the cells into the PBMC-humanized mice or control NOG mice." (PMID 36810288, 2023). "Reciprocally, MTSS1 overexpression reduced the protein levels of PD-L1 in lung cancer and bronchial epithelial cells." (PMID 36810288, 2023). "Importantly, genetic ablation of Mtss1 accelerated the development of KrasG12D-induced lung cancer in the mice, as evidenced by increased tumor burden in the lungs and lung weights in age-matched mice." (PMID 36810288, 2023). "Thus EGFR–KRAS signaling stabilizes PD-L1 protein, at least partially, by suppressing MTSS1 protein expression in lung cancer." (PMID 36810288, 2023). "Of these genes, metastasis tumor suppressor-1 (MTSS1) was of special interest because this gene had the highest total context score, and its role in epithelial-mesenchymal transition has been greatly documented in lung cancer." (PMID 30224667, 2018). "Thus, we assessed the effect of Mtss1 knockout in mice on lung cancer." (PMID 36810288, 2023). "Notably, a significant downregulation of MTSS1 in lung cancer was also observed." (PMID 36810288, 2023). "MTSS1 levels were lower in lung cancer tumors with BM than in those without BM." (PMID 30224667, 2018).
lymph node metastasis (4 papers, 2010 to 2018). "As lymph node metastasis is one of the most important prognostic factors, we next explored possible correlations between MTSS1 expression levels and lymph node metastasis." (PMID 21696600, 2011). "Moreover, MTSS1 expression was positively correlated with the lymph node metastasis ratio of LAD." (PMID 30224667, 2018).
lymphoma (4 papers, 2013 to 2020). A malignant (clonal) proliferation of B- lymphocytes or T- lymphocytes which involves the lymph nodes, bone marrow and/or extranodal sites. "Oncomine67 portal was used to search for the expression levels of MTSS1 in lymphomas and leukaemias." (PMID 30858428, 2019). "While earlier studies of MTSS1 had mainly focused on solid cancers and lymphomas, this is the first study in myeloid neoplasms providing evidence for an important function of MTSS1 as a potential tumor suppressor in AML and as a predictor of clinical outcome." (PMID 25996952, 2015). "However, this is, to the best of our knowledge, the first time DSP, FZD8, KCNH2, MTSS1, and PPP1R14A have been reported to be methylated in lymphoma." (PMID 24260260, 2013).
Ataxia (3 papers, 2022 to 2025). Ataxia refers to impaired coordination of voluntary muscle movement. "It is noteworthy that Itpr1, Calb1, Mtss1, and Kcnma1 are known to cause ataxia when mutated in human or mouse models." (PMID 38673939, 2024). "Moreover, Mtss1 was identified as an ataxia gene linked to multiple spinocerebellar ataxias (SCAs) positioning it as a potential therapeutic target for SCAs." (PMID 41288860, 2025). "In SCA1 and SCA2 the expression levels of Mtss1 were found to be greatly reduced suggesting a role of Mtss1 as an ataxia gene linking multiple SCAs." (PMID 41288860, 2025). "Mtss1, which encodes an I-BAR containing membrane curving protein involved in the formation of the dendritic arborization of PCs, induces ataxia and elevated levels of activated SFK when mutated in mice." (PMID 38673939, 2024). "While our experiments focus on a SCA14 mouse model, the reported involvement of Mtss1 in other types of ataxia suggests that the PKCγ-Mtss1 molecular mechanisms described here could be relevant for multiple SCAs." (PMID 41288860, 2025). "A key role for MTSS1/SRC family kinase dysregulation was also shown in Purkinje neurons survival and ataxia progression in SCA1 and SCA2 mouse models." (PMID 35892334, 2022). "Interestingly, among the 24 PC genes with restored expression, seven genes (Abr, Calb1, Htr1b, Itpr1, Kcnip1, Kcnma1, and Mtss1) were part of a group of 80 PC-type-specific downregulated genes common to the SCA1, SCA2, and SCA7 mouse models and composed an ataxia molecular signature." (PMID 38673939, 2024).
B-cell lymphomas (3 papers, 2015 to 2021). "Mtss1 knockout mice displayed aberrancies in the B-cell compartment and ultimately developed B-cell lymphomas." (PMID 33782537, 2021). "MTSS1 was also implicated in hematological malignancies: it was downregulated in human B-cell malignancies, and Mtss1 knockout mice developed B-cell lymphomas." (PMID 34029637, 2021). "Mtss1 knockout mice, however, developed B-cell lymphomas, pointing toward an anti-oncogenic role of this gene also in the hematopoietic system." (PMID 33782537, 2021). "Specifically, MTSS1 knockout mice have an increased propensity to develop aggressive B cell lymphomas." (PMID 25996952, 2015). "Mice with targeted disruption of MTSS1 (MTSS1 knockout mice) show altered cell polarity, motility, receptor signaling, and membrane ruffling, altered cytoskeleton organization and cell-cell junctions, and they ultimately develop aggressive B cell lymphomas." (PMID 25996952, 2015). "Furthermore, MTSS1 was found to be downregulated in cells from patients with B cell lymphomas and pre-B-ALL." (PMID 25996952, 2015).
chronic myeloid leukemia (3 papers, 2021 to 2023). "MTSS1 expression was also reduced in diagnostic samples from patients with chronic myeloid leukemia (CML), and restored at remission." (PMID 33782537, 2021). "Similarly, in chronic myeloid leukemia, MTSS1 is downregulated, and re-expression of MTSS1 affects leukemic cell motility, tumor growth, and chronic myeloid leukemia development in vitro." (PMID 37920825, 2023).
depression (3 papers, 2019 to 2024). "We identified a MTSS1 variant (rs1017432) that may be genetically associated with MoA and comorbid depression." (PMID 36704746, 2022). "The most significant hits were for the number of manic episodes, with SLC13A3 as top gene in BP-I and TNRC6C in BP-II, followed by the number of depressive episodes, with MTSS1 as top gene in BP-I and DNAH14 in BP-II." (PMID 38865039, 2024).
diffuse large B-cell lymphoma (3 papers, 2022 to 2024). "Low expression of MTSS1 correlates with poor prognosis for patients with diffuse large B-cell lymphoma." (PMID 37920825, 2023). "Expression of this miRNA was correlated with diffuse large B-cell lymphoma, which promotes proliferation, invasion and metastasis through the target inhibition of metastasis suppressor 1 (MTSS1)." (PMID 36009551, 2022).
esophageal squamous cell carcinoma (3 papers, 2011 to 2015). Esophageal squamous cell carcinoma (ESCC) is a type of esophageal carcinoma (EC) that can affect any part of the esophagus, but is usually located in the upper or middle third. "The prognostic value of MTSS1 expression has also been demonstrated for esophageal squamous cell carcinoma in which patients with high MTSS1 expression levels had a favorable prognosis compared to those who had reduced MTSS1 expression levels." (PMID 25996952, 2015). "Until now, there has been no research reporting the role of MTSS1 in oesophageal squamous cell carcinoma (ESCC)." (PMID 21696600, 2011). "Recent studies have demonstrated the clinical significance of MTSS1 in certain type of cancers, yet the clinical relevance of MTSS1 in oesophageal squamous cell carcinoma (ESCC) has not been reported." (PMID 21696600, 2011).